PYY (peptide YY)
Diseases named in the same sentence as PYY in open-access papers (continued):
Sharing a sentence is not in itself a finding about the gene and the disease.
Anorexia (continued). "A preclinical study shows that TJ-48 inhibits the production of IL-6, MCP-1, PYY, and GLP-1 and ameliorates cancer-induced anemia using a CT-26 tumor-bearing mouse cancer anorexia/cachexia model." (PMID 35736467, 2022). "A study implies that TJ-48 used as a treatment for anorexia regulates the levels of glucagon-like peptide-1 (GLP-1) and peptide tyrosine tyrosine (PYY), which are satiety stimulators." (PMID 35736467, 2022). "At a molecular level PYY acts through engaging the Y2 receptors on the NPY ARC neurons reducing their activity and thus pushing the balance towards anorexia." (PMID 33572661, 2021). "Direct injection of exogenous intestinal hormones CCK, PYY, GIP, and GLP-1 can trigger anorexia behavior in mice." (PMID 34437383, 2021). "PYY and GLP-1 can also induce anorexia via interacting with the vagus nerve and the promoting the activity of POMC neurons that secrete anorectic peptides." (PMID 33572661, 2021). "In summary, this study found that DON can acutely induce anorexia in mice within 1–3 h, and it can also acutely increase the concentration of intestinal hormones CCK, PYY, GIP, and GLP-1 in mice plasma." (PMID 34437383, 2021). "We found that 1 and 2.5 mg/kg·bw of DON can acutely induce anorexia and increase the plasma intestinal hormones CCK, PYY, GIP, and GLP-1 in mice within 3 h." (PMID 34437383, 2021). "We also proved that the intestinal hormones CCK, PYY, GIP, and GLP-1 can trigger anorexia behavior in mice, and the receptors of these hormones play an essential role in the antifeedant response induced by DON." (PMID 34437383, 2021). "DON crosses the blood–brain barrier and targets the hypothalamus to produce anorexia behavior, and it affects the secretion of gut hormones, such as CCK, PYY, GLP-1, and 5-HT, which target the hypothalamus via the brain-gut axis to regulate appetite." (PMID 32878107, 2020). "In this species, DON also induces the release of the satiety hormones, peptide YY (PYY) and cholecystokinin (CCK), proposed as critical mediators of DON-induced anorexia." (PMID 24859243, 2014). "Our study demonstrates that the SJDBT ameliorates cancer-induced anorexia and cachexia in CT-26 tumor-bearing mouse model by altering the production of IL-6, MCP-1, PYY, and GLP-1." (PMID 24963216, 2014). "The relationship between exercise and appetite, known as exercise-induced anorexia, is well established and has been primarily attributed to transient increases in anorexigenic [glucagon-like peptide 1 (GLP-1) and peptide YY (PYY)] and reductions in orexigenic (ghrelin) gastrointestinal hormones." (PMID 39902404, 2025). "As demonstrated here, administrations of PYY and DON elicited anorexia, and JNJ-31020028 could attenuate anorexic response, indicating that NPY2R plays an important part in DON-induced anorexia." (PMID 34437383, 2021). "In addition, DON and T-2 also induced the release of the satiety hormones, peptide YY (PYY) and cholecystokinin (CCK), which are critical mediators of anorexia." (PMID 29535978, 2018). "As anorexia involves appetite-regulating hormones such as gut hormones (GLP-1, PYY, and ghrelin) and leptin, we further examined whether SJDBT affects their levels in serum." (PMID 24963216, 2014). "Accordingly, although peripheral secretion of PYY could play a role, DON-induced anorexia certainly also depends on the central effect of the toxin independently of its neuro-inflammatory effect." (PMID 23612752, 2013). "DON can also induce the concentration of mouse plasma intestinal satiety hormones GLP-1, GIP, PYY, and CCK to rise rapidly within 2 h, while the intestinal anorectic hormone in mouse plasma returns to normal levels after 6 h, which is consistent with the anorexia before." (PMID 34437383, 2021). "In the present study, PYY was unchanged after HYPOXIA, which does not support the theory that it contributes to high-altitude anorexia." (PMID 27313541, 2016).
type 2 diabetes (30 papers, 2013 to 2026). "Fasting and postprandial PP and PYY levels are lower in obese individuals, and individuals with type 2 diabetes have been displayed to have diminished postprandial fullness." (PMID 31275881, 2019). "For example, miglitol administration in healthy participants significantly increases GLP-1 and PYY concentrations in healthy subjects or patients with type 2 diabetes." (PMID 28805670, 2017). "PYY has been studied in two animal models of human diabetes type 2, namely ob/ob and db/dbobese diabetic mice." (PMID 23292145, 2013). "PYY-based interventions may offer distinct advantages for specific patient populations with type 2 diabetes (T2D) who exhibit heterogeneity in response to incretin-based therapy." (PMID 41228539, 2025). "In conclusion, our data indicate that GPR119 agonism with GSK263 causes substantial changes in circulating total PYY levels, but it did not improve glycemic control in subjects with type 2 diabetes when dosed alone or with metformin or sitagliptin." (PMID 24699248, 2014). "In diabetes type 2, at least inanimal models, PYY cells and synthesis may be decreased to compensate for the slowintestinal transit and constipation." (PMID 23292145, 2013). "Butyric acid is of particular interest in type 2 diabetes as animal studies report it improves glucose homeostasis by inducing gut production of GLP-1 and peptide YY (PYY) as well as protecting the gut barrier function." (PMID 32440730, 2020). "We conclude that GSK263 did not improve glucose control in type 2 diabetics, but it had profound effects on circulating PYY." (PMID 24699248, 2014). "This suggests that treatment with 16 g ITF/d for as long as 6 weeks should have enhanced the response of PYY in the present trial, and indicates that ITF may have a different impact in type 2 diabetes than in non-diabetic populations." (PMID 34589204, 2021).
Anxiety (18 papers, 2008 to 2025). Intense feelings of nervousness, tension, or panic often arise in response to interpersonal stresses. "In the present study, we examined the associations of NPY, PYY, and PP plasma levels with anxiety, depressiveness and perceived stress in obese patients." (PMID 33192409, 2020). "We conclude that in AN, refeeding for 2 weeks was associated with improvements in PYY, appetite and baseline anxiety, while increased ghrelin, bloating and postprandial anxiety persisted." (PMID 30597915, 2018). "PYY signals to the brain to attenuate food intake, anxiety, and depression-related behavior and is thought to be a satiety signal, reducing food intake." (PMID 32899507, 2020). "Compared with HCs, in patients with AN at Wk0, baseline ghrelin, PYY, fullness, bloating and anxiety were higher, and hunger less, and in response to the meal, ghrelin, bloating and anxiety were greater, and hunger less (all p < 0.05)." (PMID 30597915, 2018). "After two weeks of refeeding, there was no change in baseline or postprandial ghrelin or bloating, or postprandial anxiety, but baseline PYY, fullness and anxiety decreased, and baseline and postprandial hunger increased (p < 0.05)." (PMID 30597915, 2018). "Under conditions of DSS-induced colitis, PYY influences emotional-affective behavior in a sex-dependent manner, because anxiety-like behavior is modified only in female PYY knockout mice while depression-like behavior is altered only in male PYY knockout mice." (PMID 29213271, 2017). "Genetic deletion of PYY enhances depression-like behavior in mice, whereas anxiety-related behavior stays unaltered." (PMID 29213271, 2017). "In addition, SCFAs stimulate EECs to releases neuropeptide Y, peptide YY, and other gut hormones such as ghrelin, which attenuate anxiety- and depression-like behavior." (PMID 35456041, 2022). "Therefore, in the present study we investigated the relationship between circulating levels of the members of the NPY family (NPY, PYY, PP) and psychometrically evaluated anxiety, depressiveness and perceived stress in obese psychosomatic patients." (PMID 33192409, 2020). "High protein diets are related to complex agonistic interaction between peptide YY3-36 (PYY3-36) and NPY Y2 receptors; receptors that are co-expressed in the amygdala and responsible for causing anxiety, in addition, to modulating signaling belonging to the mesolimbic dopaminergic reward pathways." (PMID 31336641, 2019). "In addition, physiological factors (hormones such as GLP-1, PYY, and leptin), psychiatric conditions (depression, anxiety), and behavioral aspects (maladaptive eating behaviors, binge eating, and FA) may also contribute to suboptimal WL after BS." (PMID 40647219, 2025). "Microbiota-mediated enteroendocrine and enterochromaffin cells in the intestinal epithelium can release multiple gut hormones, including 5-HT, PYY, GLP-1, CCK, and ghrelin, which regulate multiple brain disorders, such as anxiety and depression." (PMID 38057297, 2023). "Abnormal expression of brain-gut peptides, like ghrelin, NPY, CCK, PYY, and GRP, in the peripheral and central systems can lead to depression, anxiety, gastrointestinal diseases, and metabolic disorders." (PMID 37511879, 2023). "Contrarily, many anorexigenic enteroendocrine signals, such as peptide YY (PYY) and glucagon-like peptide-1 (GLP-1), suppress reward function and can increase anxiety-like behaviour." (PMID 34202073, 2021). "The NPY family of neuropeptides, including NPY, peptide YY (PYY), and pancreatic polypeptide (PP), has been shown to elicit diverse biological functions including hypothalamic control of food intake, anxiety and sedation." (PMID 18836554, 2008). "While the deletion of PYY increases depression-like behavior but does not affect anxiety, peripherally administered PP promotes extinction learning of cued fear by acting on central Y4 receptors in mice." (PMID 33192409, 2020).
Anxiety (continued). "After a 4 h fast, appetite perceptions, GI symptoms, state anxiety, and plasma acyl-ghrelin, cholecystokinin (CCK), peptide tyrosine tyrosine (PYY) and pancreatic polypeptide (PP) concentrations were assessed at baseline and in response to a mixed-nutrient test-meal (479 kcal)." (PMID 30597915, 2018). "Furthermore, the surgery-induced hormonal shifts, particularly increases in glucagon-like peptide-1 (GLP-1), peptide YY (PYY), and reductions in ghrelin levels, have been shown to positively affect mood, reduce anxiety, and alleviate obsessive-compulsive symptoms." (PMID 39863849, 2025).
anorexia nervosa (17 papers, 2007 to 2025). A disorder most often seen in adolescent females characterized by a refusal to maintain a minimally normal body weight, an intense fear of gaining weight, a disturbance in body image, and, in postmenarcheal females, the development of amenorrhea. "Pancreatic polypeptide, which was elevated in patients, has been linked to anorexia nervosa, and another member of the pancreatic polypeptide family, peptide YY, was (marginally) positively related to depressive symptoms in older adults." (PMID 32779563, 2022). "Bone loss in anorexia nervosa and following bariatric surgery is associated with an elevated circulating concentration of the gastrointestinal, anorexigenic hormone, peptide YY (PYY)." (PMID 31306808, 2019). "Previous studies evaluated the association between PYY and bone density in metabolic diseases that affect PYY such as anorexia nervosa or in special groups such as athletes." (PMID 24053729, 2013). "For instance, the greater circulating PYY levels in patients with anorexia nervosa are significantly associated with altered bone homeostasis and diminished bone mass, particularly in the spine." (PMID 22792209, 2012). "Moreover, anorexia nervosa is associated with changes in hormones with an impact on bone quality, including anorexigenic hormones such as leptin, peptide YY and GLP1." (PMID 39201093, 2024). "In two studies on anorexia nervosa patients, PYY was negatively associated with bone density." (PMID 24053729, 2013). "Furthermore, both plasma CCK and PYY concentrations are elevated in patients with chronic nutrient deprivation, malnutrition, and anorexia nervosa, conditions that are known to be associated with a high prevalence of delayed GE." (PMID 18154642, 2007). "In individuals with a low body weight, such as amenorrhoeic athletes and patients with anorexia nervosa, PYY levels are higher compared to controls." (PMID 39595594, 2024). "Higher total plasma PYY levels were reported in patients with anorexia nervosa compared to lean, obese, or morbidly obese subjects." (PMID 36313742, 2022). "Increased cortical bone porosity is frequently associated with high bone turnover osteoporosis and fragility fracture and has been reported in patients with anorexia nervosa, who have elevated PYY levels." (PMID 31306808, 2019). "Anorexia nervosa (AN) presents an adaptive appetite regulating profile including high levels of ghrelin and 26RFa (orexigenic) and low levels of leptin and PYY (anorexigenic)." (PMID 25798605, 2015). "PYY is considered as a potential contributor to the low bone mass of anorexia nervosa, where PYY levels are reported to be increased." (PMID 22792209, 2012). "The present study investigated plasma levels of gut-brain axis peptides ghrelin, obestatin, NPY and PYY after consumption of a high-carbohydrate (HC) and high-protein (HP) breakfast in patients with anorexia nervosa, bulimia nervosa and in healthy controls." (PMID 22681985, 2012). "Nutritional deprivation is likely to be relevant since inadequate nutritional support is common in critically ill patients, fasting slows GE even in healthy subjects, and fasting CCK and PYY concentrations are higher in patients with anorexia nervosa and malnutrition." (PMID 18154642, 2007). "The PYY levels were 25.49 ± 9.79 pg/mL among adolescents with anorexia nervosa and 18.46 ± 9.81 pg/mL in healthy adolescents, which is a much lower concentration than in our study, but this difference may occur due to technical differences in the tests used for the analysis." (PMID 36313742, 2022). "While some studies in mice suggest that incretins like GLP-1 and GIP may have a beneficial effect on bone, a negative association between bone formation markers and PYY has been reported among adolescents with anorexia nervosa." (PMID 32545353, 2020). "An inverse relationship has been reported between circulating PYY levels and BMD in patients with anorexia nervosa and following bariatric surgery." (PMID 31306808, 2019).
anorexia nervosa (continued). "Importantly, these findings suggest that the changes in circulating PYY levels observed in clinical conditions, such as anorexia nervosa, amenorrhea and patients who have undergone bariatric surgery, may contribute to the alterations in bone mass in these patients." (PMID 22792209, 2012). "Status of anorexia nervosa was found to be positively correlated with plasma levels of ghrelin, obestatin, NPY and PYY and negatively correlated with BMI, percent of body fat and weight." (PMID 22681985, 2012). "Additionally, PYY inhibits osteoblast activity, contributing to lower BMD in athletes and patients with anorexia nervosa." (PMID 39595594, 2024). "As status of anorexia nervosa was found to be positively correlated with plasma levels of ghrelin, obestatin, NPY and PYY, we suppose that all these hormones are included in pathology of eating disorder and their levels are changed probably as a consequence of eating disorder." (PMID 22681985, 2012). "It has recently been demonstrated that peptide YY (PYY), glucagons-like peptide 1 (GLP-1) and ghrelin behave in opposite ways between patients of anorexia nervosa and constitutionally thin subjects, suggesting that endocrine changes precede malnutrition in anorexia nervosa." (PMID 22128818, 2011).
metabolic syndrome (14 papers, 2014 to 2025). A cluster of metabolic risk factors for CARDIOVASCULAR DISEASES and TYPE 2 DIABETES MELLITUS. "Metabolic bariatric surgery induces significant changes in gastrointestinal hormone secretion, thereby including GLP-1 and PYY, which improve glycemic control and manage metabolic syndrome." (PMID 40342858, 2025). "These documented effects do not diminish with prolonged use, creating potential for the application of PYY in the treatment of metabolic syndrome." (PMID 39408213, 2024). "In addition, group B (HOMA-IR ≥ 2.5) had significantly more preoperative biomarker abnormalities (other than dyslipidemia) than group A, including leptin, ghrelin, PYY, insulin, RBP4, and LGr." (PMID 36203073, 2022). "Critically, the 3 h preload ISO optimizes postprandial metabolism by sustaining PYY levels and amplifying SME—a novel finding with significant implications for dietary approaches in metabolic syndrome." (PMID 40806123, 2025). "The observed link between PYY and the TG/HDL ratio, a marker of risk for metabolic syndrome, is a novel finding and suggests that negative energy balance favorably influences biomarkers for metabolic syndrome." (PMID 29143803, 2017).
depression (13 papers, 2017 to 2025). "Indeed, one study analyzing protein degradation products showed reduced unbranched-chain fatty acids (such as butyrate), while two studies showed increased levels of branched-chain fatty acids that led to increased PYY production, which is linked to increased depression and reduced appetite." (PMID 33126427, 2020). "This phenotype is consistent with impaired stress coping and enhanced depression-like behavior seen in PYY(−/−) mice." (PMID 28106168, 2017). "A reduction of the central NPY level and/or function was observed in experimental and clinical depression, whereas central administration of NPY or Y1R agonist [Leu31,Pro34]-PYY produced antidepressant-like effects in rats and mice; moreover, these effects were blocked by Y1R antagonists." (PMID 27975125, 2017).
Hyperglycemia (12 papers, 2020 to 2025). An increased concentration of glucose in the blood. "T2DM still has potential through chronic hyperglycemia, oxidative stress, and advanced glycation end products (AGEs) to disrupt the physiological interaction between PYY and DPP-4; thus, further human studies should address this question." (PMID 40142315, 2025). "Fourth, decreases in the secretion of peptide YY and glucagon-like peptide 1 (GLP-1) by fast eating may cause postprandial hyperglycemia." (PMID 34062802, 2021). "GLP-1, GIP, and PYY are secreted basolaterally by enteroendocrine cells and have beneficial functions for host metabolism, and their absence would likely permit a change in glucose homeostasis, leading to hyperglycemia and an increase in food intake." (PMID 32051237, 2020). "In conclusion, single bouts of LV-HIIE and CME increased circulating total GLP-1 concentrations but did not influence overall appetite perceptions or circulating total PYY and AG concentrations in white Europeans and South Asians with non-diabetic hyperglycaemia." (PMID 40425789, 2025). "In addition, PYY may also improve islet secretory function post-MBS, and GLP-1 is known to increase glucose-dependent insulin secretion and suppress glucagon during hyperglycemia, all factors that likely contribute to the metabolic improvements seen in participants of IMPROVE-T2D." (PMID 39911520, 2025).
Hypertension (9 papers, 2018 to 2024). The presence of chronic increased pressure in the systemic arterial system. "Additionally, an elevation of some gut hormones, such as GLP-1 and peptide YY, may cause a diuretic and natriuretic effect on the kidney, contributing to hypertension remission." (PMID 37178225, 2023). "In addition, arterial hypertension was more often present in patients with high PYY levels, which might be attributable to direct vasoconstrictive effects of the peptide resulting in increased blood pressure under experimental conditions." (PMID 33291235, 2020).